MUC1 (mucin 1, cell surface associated)
Diseases named in the same sentence as MUC1 in open-access papers (continued):
Sharing a sentence is not in itself a finding about the gene and the disease.
cancer (continued). "The TF-bearing protein MUC1 is a large and heavily glycosylated transmembrane mucin protein that is overexpressed by most cancer cells of epithelial origin." (PMID 27066458, 2016). "Several MUC1-binding ligands have been developed and utilized for targeted delivery of chemotherapeutics or phototoxin to MUC1-positive cancer cells in vitro." (PMID 27203221, 2016). "It is unclear the reason(s) for this disparity in the cancer cells, but in KCM, BxPC3 and Capan-1 cells, the cytoplasmic tail motif of MUC1 associated directly with the promoter region of the Abcc1/ABCC1 gene." (PMID 27029067, 2016). "TTA1, AS1411 and MUC-1 are more successful aptamers that were reported to specifically bind to cancer cells or cancer tissues." (PMID 27973403, 2016). "The importance of altered MUC1 glycosylation extends also to its role as a promoter of chronic inflammatory conditions that lead to malignant transformation and cancer progression." (PMID 27754373, 2016). "The link between aberrant pattern of MUC1 glycosylation and inflammation-related cancer has been extensively demonstrated in our laboratory also in in vivo models." (PMID 27754373, 2016). "MUC1 is an attractive antigen for this purpose, due to its high level of expression by the majority of human cancers and its reported immunogenicity." (PMID 26788922, 2016). "That is why the National Cancer Institute has placed MUC1 as a second prioritized cancer antigen for translational research." (PMID 27472370, 2016). "We previously determined that in sera of cancer patients with MUC1+ tumors, there are anti-MUC1 antibodies specific for this sequence." (PMID 27545199, 2016). "Subsequently, a SPION-based approach has been extended to other cancer cells by generating a tertiary complex, combining SPIONs with the anti-MUC-1 5TR1 aptamer and the anthracycline drug Epirubicin." (PMID 27827876, 2016). "We extended our analyses to human cancer cells which natively express high levels of the MUC1-TM protein." (PMID 27768738, 2016). "Aberrantly glycosylated MUC1 has shortened core-1 based glycans resulting from termination by sialyl groups that prevent cancer cells from forming core-2 based glycans, necessary to become hyperglycosylated MUC1." (PMID 27472370, 2016). "Many studies have reported that the binding of galectin-3 with MUC1 triggers MUC1-dependent intracellular signaling in cancer cells and facilitates adhesion of cancer cells to each other and to endothelial cells." (PMID 27754373, 2016). "MGL is able to interact with various types of cancer-related-mucins from which two are extensively studied, namely mucin 1 (MUC1) and mucin 2 (MUC2)." (PMID 27153100, 2016). "Three component fully synthetic MUC1 glycopeptide cancer vaccines have been synthesized by conjugating MUC1-VNTR with different TACAs serving as B cell epitopes along with various T helper cell epitopes and different TLR agonists as adjuvant." (PMID 27472370, 2016). "The studies reported here demonstrate unequivocal expression of the frameshifted MUC1-ARF protein in MUC1 cell transfectants, in MUC1-expressing cancer cell lines, and in sections of normal and malignant human tissues." (PMID 27768738, 2016). "To further confirm the functional relevance of MUC-1 in NF-κB-mediated signaling in M2-TAM-induced cancer malignancy, we used silencing techniques to inhibit Muc1 expression in M2-TAM-co-cultured A549 and H441 cells." (PMID 27276704, 2016). "A wide variety of MUC1 glycopeptide anti-cancer vaccines have been formulated by many research groups." (PMID 27472370, 2016).
cancer (continued). "We had previously tested MUC1 peptide vaccines composed of the cancer-specific core peptide antigen consisting of 5 copies of the unglycosylated 20mer tandem repeat sequence from the VNTR region, combined with different adjuvants." (PMID 27545199, 2016). "When treated with Apt-Td-Dox, significantly more doxorubicin was observed in the MUC1-positive cancer cells compared with the MUC1-negative control cells, indicating that a targeted-delivery of doxorubicin occurred in vitro." (PMID 27203221, 2016). "On the top of the list of tumour antigens suitable for DC-based cancer therapy is WT1 protein (overexpressed in AML) or highly immunogenic MUC-1 (overexpressed and/or hypoglycosylated in numerous cancer types)." (PMID 27212807, 2016). "Surprisingly, however, little is known about epigenetic regulation of the MUC1 gene in cancer cells." (PMID 26930718, 2016). "For these reasons, synthetic glycoconjugate vaccines are an appropriate avenue for anti-MUC1 cancer vaccine development." (PMID 27472370, 2016). "MUC1 is considered a high-value molecular target for cancer treatment because it is widely expressed in most adenocarcinomas, including cancers of breast, lung, colon, prostate, stomach, pancreas, and ovary." (PMID 27203221, 2016). "MUC1 protein expression has been found to be significantly elevated in several cancers including CaP and is usually accompanied by altered glycosylation." (PMID 27846218, 2016). "In a recent study, AuNPs have been combined to graphene oxide (GO) to generate a novel anti-MUC-1 aptamer-gold nanoparticle-hybridized GO nanocomposite (Apt-AuNP-GO) able to induce targeted cancer cell PTT at ultralow concentrations." (PMID 27827876, 2016). "Prior studies have demonstrated that MUC1 in cancer cells is under glycosylated, exposing the protein backbone and increasing the proteinogeneic accessibility by ligands such as antibodies or aptamers." (PMID 27203221, 2016). "MUC1 is produced by inflammatory lung macrophages which subsequently secrete TNFα and promote cancer progression." (PMID 27276704, 2016). "A tripartite cancer vaccine candidate, containing a quaternary amino acid (α-methylserine) in the most immunogenic domain of MUC1, has been synthesized and examined for antigenic properties in transgenic mice." (PMID 29910919, 2016). "MUC1 is normally present on the apical surface of the secretory epithelium; however, its expression levels and cellular localization are altered in malignant tumors." (PMID 27846863, 2016). "These new interactions of MUC1 with various proteins increase its internalization and enable nuclear localization, leading to altered signaling in cancer cells." (PMID 27754373, 2016). "The identification of a sufficiently immunogenic antigen has been a major obstacle for the development of a clinically-effective cancer vaccine, though several potential vaccines (such as Muc1 and mesothelin) have reached human trials." (PMID 27343548, 2016). "In our data, we show that there is an increase in MUC1 expression level when comparing normal endometrial samples to primary carcinoma samples as well as to recurrent EMCAR and metastatic lesions, further supporting these data." (PMID 27618037, 2016). "This feature, together with the fact that MUC1 is overexpressed in most carcinoma cells, makes MUC1 an attractive therapeutic target." (PMID 27203221, 2016). "Our results reveal a new mechanism in which MUC1 promotes cancer progression by mediating Smad3 signaling." (PMID 25714018, 2015). "Muc-1 levels are elevated in the majority of patients with PC, and Muc-1 plays a key role that affects oncogenesis and the motility, metastasis, metabolism, and growth of cancer cells." (PMID 26579537, 2015). "The presence of this fusion transcript in TCGA cancer samples is supported by 25 paired “chimeric” reads with one read mapping to MUC1 and the other to TRIM46 (using GRCh37/hg19)." (PMID 26492273, 2015).
cancer (continued). "Mucin 1 (MUC1) protein is considered as one of the most important targets in cancer therapy because of its high level of expression." (PMID 28536411, 2015). "The present study indicates a novel mechanism by which MUC1 promotes cancer progression and provides an attractive target for HCC therapy." (PMID 25714018, 2015). "MUC-1 is a heavily glycosylated, type 1 transmembrane protein that is overexpressed in a large number of cancers including colorectal, pancreatic, and ovarian." (PMID 25806106, 2015). "The antigens incorporated into self-adjuvanting cancer vaccines range from clustered copies of the TN antigen to truncated MUC1 B cell epitopes to full copies of glycosylated MUC1 VNTR." (PMID 26557640, 2015). "MUC1 expression is a topic of great interest in a variety of cancer types, and particularly in breast." (PMID 26424146, 2015). "Based on these findings, MUC1 has been applied to clinical practice as a cancer biomarker for diagnosing, staging and monitoring relapse following therapy." (PMID 26367866, 2015). "Many investigations have shown that aberrant expression of MUC1 in gastrointestinal cancer tissue has clinicopathological and biological importance in cancer disease." (PMID 26451373, 2015). "It has also been demonstrated that DCs are able to recognize cancer-specific glycosylation changes of the mucin 1 (MUC1), in particular, the carbohydrate sialyl Lewis X, and the sialyl TN epitope through MGL and DC-SIGN." (PMID 26379663, 2015). "In the metabolism of cancer cells, MUC1 modulate the expression of glycolytic pathway enzymes by interacting with HIF-1αand enhances the expression of genes pertaining to glucose uptake and metabolism." (PMID 26367866, 2015). "Although the exact mechanism by which MUC1/CIN85/Cbl complex promotes and regulates cancer progression is still under investigation, this association is highly related to advanced stage of tumors and lymph node metastasis." (PMID 25675408, 2015). "For these reasons, MUC1 is considered a promising antigen in the development of effective cancer vaccines." (PMID 26557640, 2015). "Although transient MUC1 activity functions to reduce inflammation, long-term overexpression promotes aggressive phenotypes in human cancers." (PMID 26147830, 2015). "The functional role of MUC1 in malignancy has been widely studied and several lines of evidence suggest that MUC1 is potentially correlated with the development, invasiveness and metastasis of cancer." (PMID 26367866, 2015). "The results demonstrated that the antibody reacted with MUC1 on the membrane of the cancer cells in vivo." (PMID 25815753, 2015). "Immunocytochemistry with fluorophore conjugated anti-MUC1 antibody demonstrated fluorescent areas on the membrane of Panc-1 cancer cells." (PMID 25815753, 2015). "Increasing evidence reveals that the extracellular subunit of MUC1 is shed from cancer cell membrane and released into the blood stream; and aberrant expression of T antigen regulates MUC1 trafficking and recycling." (PMID 25762620, 2015). "MUC1 was identified on the surface of many types of cancer cells, for example, breast and ovarian, lung, pancreatic, and prostate cancers." (PMID 26509158, 2015). "MUC1, as an oncogene, is involved in several signaling pathways to promote cell migration and invasion of various cancers." (PMID 26057631, 2015). "Despite its antenna-like physical manifestation that in principle lends well to therapeutic targeting of mucin-expressing tumors, MUC1 has been underexploited in targeted cancer therapy." (PMID 26147830, 2015). "This drug-encapsulated aptamer enhanced in vitro drug delivery, specifically, to the MUC1 expressing cancer cells." (PMID 28536411, 2015). "TGF-β signaling has been considered a therapeutic target for many cancers, and our results demonstrate that the MUC1 oncogene, upstream of the TGF-β signaling is a more attractive therapeutic target for HCC." (PMID 25714018, 2015).
cancer (continued). "The overexpression of MUC1 in cancers possibly leads to chimeric RNA expression as they both involve the same promoter." (PMID 26492273, 2015). "The major goals of this work were to identify optimal conditions for nanoparticle functionalization and to demonstrate the feasibility of photothermal ablation of MUC1 positive cancer cells via biofunctionalized AuNRs." (PMID 26147830, 2015). "Several mucin (MUC) glycoproteins have been shown to be overexpressed during cancer and have therefore been targeted in cancer vaccines, including MUC1, MUC4, MUC5AC, and MUC16." (PMID 26557640, 2015). "MUC1 is frequently overexpressed in various cancers including breast, ovarian, lung, and colon cancer." (PMID 25815753, 2015). "Recent studies have highlighted the overexpression of mucin 1 (MUC1) in various epithelial carcinomas and its role in tumorigenesis." (PMID 26147830, 2015). "MUC1 (CD227) is a TAA that is overexpressed on a majority of human carcinomas and several hematologic malignancies." (PMID 26374823, 2015). "Mucin 1 (MUC1) is a heterodimeric protein that is aberrantly expressed in diverse human carcinomas and certain hematologic malignancies." (PMID 26267657, 2015). "Taken together, combining antibodies with drugs is more effective strategy in treatment of carcinoma with high expression of MUC1." (PMID 26112902, 2015). "MUC1 is normally expressed at the surface of glandular epithelial cells and, in carcinomas, it is overexpressed and aberrantly hypoglycosylated." (PMID 26374823, 2015). "The difference in molecular weights seen in the human DCs versus the SW620 human carcinoma cells is most likely due to the differential glycosylation of the MUC1 protein." (PMID 26374823, 2015). "Up-regulation of MUC-1, a marker of glandular cells, promotes cell proliferation and invasion through epithelial-to-mesenchymal transition in some late-stage carcinomas including urothelial cancer." (PMID 26514209, 2015). "Patients with premalignant and malignant conditions of the genital tract (mostly uterus and ovaries), as well as those affected with other cancers have increased MUC1 antibody titers, although the intensity of these responses is variable." (PMID 25078979, 2014). "Direct regulation of some oncogenes involved in cancer cell invasion and metastasis, like MUC1, FSCN1, NEDD9 and SOX9, by miR-145 has been identified in many cancers 90–93." (PMID 25124875, 2014). "Increased MUC1 expression has been shown to inhibit integrin-mediated cell adhesion between cancer cells and ECM and to decrease adhesion to type I collagen." (PMID 25109922, 2014). "Intriguingly, it is also known that MUC1 facilitates cancer cell survival under hypoxic and nutrient-deprived conditions by regulating glucose and lipid metabolism and the cellular energy state." (PMID 24810688, 2014). "We have previously reported that the expression of MUC1 was observed in all cancer cells from all 55 pancreatic ductal adenocarcinomas as well as 2 liver metastases by immunohistochemistry." (PMID 24947606, 2014). "Deregulated expression of MUC1 is a prominent characteristic of various types of cancers and inflammatory diseases." (PMID 24671186, 2014). "MUC1 is a membrane-bound glycoprotein that is overexpressed and aberrantly glycosylated in most epithelial cell-derived cancers, including genital tract tumors." (PMID 25078979, 2014). "Further studies are clearly required to better understand new roles of nuclear MUC1-ECD in cancer cells." (PMID 24504508, 2014). "MUC1-targeted immunotherapy is under development for several cancers and has been administered so far to about 1200 patients, while more than 2000 patients are currently enrolled in ongoing clinical trials." (PMID 25078979, 2014). "MUC1 is a tremendous oncoprotein that destroys apoptosis execution pathways, one of the most important anti-cancer machines contained in the cells." (PMID 24810688, 2014).
cancer (continued). "It appears clear from a series of studies, particularly in cancer cells, that the MUC1 CT participates in signaling pathways." (PMID 24968021, 2014). "In 2009, the cancer antigen prioritization project of the National Cancer Institute ranked Wilms tumor 1 (WT1) and mucin 1, cell-surface associated (MUC1) as the highest and second highest priority antigens, respectively." (PMID 25526950, 2014). "GALNT3 knockdown was also accompanied with increase of the cell adhesion molecules β-catenin and E-cadherin, which are normally suppressed by MUC1 in cancer, thus supporting the role of the GALNT3-MUC1 axis in EOC invasion." (PMID 24504219, 2014). "Their expression is increased in various cancers, and the overexpression and/or aberrant localization of MUC1 are considered as an adverse prognostic factor." (PMID 24911657, 2014). "These are normally suppressed by MUC1 in aggressive cancer cells, thus supporting the role of the GalNAc-T3/MUC1 axis in EOC invasion." (PMID 24724053, 2014). "In 2009, the cancer antigen prioritization project of the National Cancer Institute ranked Wilms tumor 1 (WT1) as the first antigen, followed by mucin 1, cell-surface associated (MUC1)." (PMID 25298213, 2014). "Previous studies showed that the binding of galectin-3 to MUC1 bearing the oncofetal Thomsen–Friedenreich antigen [Galβ1,3 GalNAc-α (TF)] increases the cancer cell adhesion to the endothelium." (PMID 24724053, 2014). "Due to the loss of polarity in cancer, MUC (MUC1 and MUC4) localize all over the cell surface, instead of restricted confinement at the apical surface." (PMID 25261375, 2014). "The expression rates in cancer lesions (more than 5% of carcinoma cells stained) were MUC1, 51.7% (31/60); MUC2, 26.7% (16/60); MUC3, 55% (33/60); MUC4, 51.7% (31/60); MUC5AC, 33.3% (20/60); MUC6, 10% (6/60) and MUC16, 8.3% (5/60)." (PMID 24722639, 2014). "MUC1 is a cell surface glycoprotein and aberrantly overexpressed in various carcinomas of epithelial origin including NSCLC, and induce gene signatures that are associated with poor survival of NSCLC patients." (PMID 25410981, 2014). "In particular, over-expression of the aberrantly glycosylated membrane bound mucins MUC1 and MUC16 is associated with several types of cancer." (PMID 24039759, 2013). "Some of these preclinical strategies are now being assessed for MUC1-based immunotherapy in clinical trials for different types of cancers." (PMID 23509794, 2013). "Similar results were reported for the MUC1 protein where EC- and CT-domains contribute separately to the cancer cell line invasiveness and metastasis." (PMID 23902727, 2013). "Monoclonal antibodies and human serum antibodies from MUC1 immunized subjects can mediate ADCC of human cancer cells." (PMID 26343966, 2013). "Different approaches have been developed to induce MUC1-specific T-cell responses in cancer patients." (PMID 23509794, 2013). "L-BLP25 is one such innovative liposomal antigen-specific cancer immunotherapy currently under development that contains 25 amino acids from the immunogenic tandem-repeat region of MUC1." (PMID 23496860, 2013). "In summary, our study provides evidence that MUC1 modulates microRNA levels to aid in cancer progression and metastasis." (PMID 24143167, 2013). "This study provides new opportunities to use small molecule inhibitors or immunotherapy to target MUC1 and CIN85 association and thus potentially reduce cancer invasion and metastasis." (PMID 24072600, 2013). "Once released into the circulation, mucins can serve as cancer biomarkers, such as CA125 (encoded by MUC16) and CA153 (encoded by MUC1)." (PMID 24324582, 2013). "WT1 and MUC1 reportedly have the first and second highest priorities, respectively, for cancer vaccines among the currently available cancer antigens." (PMID 24649223, 2013). "T-cells specific for antigenic epitopes of MUC1 that bind to HLA class I molecules have been identified and isolated from the blood and bone marrow of cancer patients." (PMID 23496860, 2013).